Y_RNA (Y RNA )
Gene: Miscellaneous RNA gene on chromosome 3 (32,045,873 to 32,045,979, forward strand). Ensembl gene ENSG00000252398.
Homologues: Orthologues: chimpanzee Y_RNA (100% identical), macaque Y_RNA (89% identical). Paralogues in human: Y_RNA (82% identical), Y_RNA (81% identical), RNY1 (80% identical), Y_RNA (80% identical), Y_RNA (79% identical), Y_RNA (78% identical), Y_RNA (77% identical), RNY1P11 (76% identical), Y_RNA (76% identical), RNY1P12 (75% identical), RNY1P13 (75% identical), RNY1P8 (75% identical), and 95 more.